CSF1R (colony stimulating factor 1 receptor)
Diseases named in the same sentence as CSF1R in open-access papers (continued):
Sharing a sentence is not in itself a finding about the gene and the disease.
diffuse-type giant cell tumor (18 papers, 2014 to 2025). "Studies of TAM depletion strategies with limited efficacy in most cancers, including CSF1/CSF1R inhibitors (e.g., PLX3397), showed limited monotherapy efficacy, except in CSF1R-driven tumors, like diffuse-type giant cell tumors." (PMID 40422244, 2025). "In another trial (NCT02923739), Emactuzumab lowered TAMs by inhibiting CSF1R, improving anti-cancer immune responses and objective response rates up to 86% in diffuse-type tenosynovial giant cell tumors in early-phase trials." (PMID 40422244, 2025). "In particular, the CSF1R inhibitor Pexidartinib approved by the FDA for tenosynovial giant cell tumour (FDA pexidartinib), was rejected by the EMA due to questionable efficacy and observed hepatotoxicity (EPAR Turalio)." (PMID 37332353, 2023). "Early phase clinical trials show promising results of CSF1R inhibitors in tenosynovial giant cell tumours (TGCT), advanced solid tumours, pancreatic cancer, and gastrointestinal stromal tumour." (PMID 37711590, 2023). "CSF1R antagonists have been reported to yield volumetric response and symptom relief in patients with inoperable diffuse type tenosynovial giant cell tumors (TCGT)." (PMID 32433669, 2020). "In diffuse-type tenosynovial giant-cell tumor showing overexpression of CSF1R, after treatment with CSF1R-blocking agents, patients experienced relevant clinical regressions." (PMID 29675018, 2018). "This has led to a phase I clinical trial evaluating anti-CSF-1R administration, which identified partial clinical responses in 5/7 patients with diffuse-type giant cell tumor." (PMID 26500776, 2015). "The clinical activity of RG7155 was evaluated in patients with diffuse-type giant cell tumor and was shown to induce a striking reduction in the CSF-1R+CD163+ macrophage population within tumor tissues." (PMID 25125485, 2014). "A phase I trial demonstrated a significant reduction in macrophage number in solid tumors after anti-Csf-1r treatment, and Csf-1r inhibition showed an improvement in clinical outcomes including improvement of symptoms in patients with diffuse-type giant cell tumors." (PMID 32038499, 2020). "Emactuzumab, a CSF1R inhibitor, improved patient-reported outcomes in a trial (NCT03193190) in diffuse-type tenosynovial giant cell tumors (dt-GCT) with durable responses (71% objective response rate) and fewer TAMs." (PMID 40422244, 2025). "Targeting the tumorigenic potential of macrophages is particularly relevant in tenosynovial giant cell tumours (TGCT), which overexpress colony stimulating factor 1 (CSF-1), leading to the recruitment of CSF-1R+ macrophages." (PMID 35327375, 2022). "A CSF-1R blocking monoclonal antibody RG7155 was shown to reduce CSF-1R+CD163+ TAMs and peripheral blood CCR2+ monocytes in phase I clinical trial in patients with diffuse-type giant cell tumor (ClinicalTrials.gov identifier NCT01494688)." (PMID 34988021, 2021). "CSF1R tyrosine kinase inhibitors (TKI) and antibodies yield response rates and tumor control in patients with diffuse type tenosynovial giant cell tumors (dTGCT)." (PMID 32433669, 2020). "Results from a phase I clinical trial demonstrated that the CSF-1R-targeted monoclonal antibody RG7155 depleted CSF-1R+ CD163+ macrophages in tumor tissues and had significant clinical benefit in patients with diffuse-type giant cell tumors." (PMID 28424405, 2017). "RG7155, a humanized monoclonal antibody of CSF-1R, strikingly reduces the CSF-1R+CD163+ macrophage infiltration in patients with diffuse-type giant cell tumor and increases CD8+ T cells and NK cells in tumor tissues." (PMID 28848446, 2017). "According to Ries (2014), patients with diffuse-type giant cell tumor, the clinical activity of RG7155 was evaluated and was revealed to induce a striking reduction in the CSF-1R + CD163+ macrophage population within tumor tissues." (PMID 29450136, 2017).
diffuse-type giant cell tumor (continued). "Among the novel CSF-1R inhibitors emactuzumab, recombinant, humanized monoclonal antibody against CSF-1R, was tested in phase 1 trials in patients with urothelial bladder cancer (NCT01494688) and diffuse-type tenosynovial giant cell tumors (dTGGT, NCT02323191)." (PMID 38794298, 2024).
amyloid (17 papers, 2016 to 2025). "While CSF1R antagonism does appear to mitigate parenchymal amyloidosis in a 5xFAD model, increased Aß has been observed in vasculature following CSF1R inhibition, resembling CAA." (PMID 40165251, 2025). "CSF1R inhibition in amyloid mouse models also reduced ICCs of TSPO-PET compared to mice with amyloidosis and intact microglia, although depletion of microglia was incomplete (66%) after seven weeks of treatment." (PMID 39238030, 2024). "A few studies reported that depleting microglia with a colony-stimulating factor 1 receptor (CSF1R) inhibitor during the disease process prevented amyloid plaque accumulation in the brains of AD animal models at an early stage of the disease." (PMID 32756440, 2020). "As proof of principle, to demonstrate biological effects in PAM function, we treated the 5xFAD mouse model of amyloidosis for 4 weeks via systemic administration (ip, 2x weekly) of HDs conjugated to a colony stimulating factor-1 receptor (CSF1R) inhibitor (D-45113)." (PMID 38711159, 2024). "We have shown that ABX-mediated gut microbiota perturbations failed to reduce Aβ amyloidosis in mice fed with a colony-stimulating factor-1 receptor (CSF-1R) antagonist that depletes microglia, indicating an essential role for microglia in the microbiota-amyloid axis." (PMID 38365827, 2024). "Additionally, when the number of DAM was reduced by the treatment of colony-stimulating factor 1 receptor (CSF1R) inhibitor, amyloid-related pathology was ameliorated, further confirming the therapeutic relevance of proinflammatory DAM in AD." (PMID 35741031, 2022). "Additionally, stimulation of these cells was also able to specifically reduce CAA load, highlighting the critical role of peripheral CSF‐1R‐dependent macrophage activity in driving amyloid clearance at the BBB." (PMID 33350588, 2021). "In contrast to the neuroprotective functions, CSF1R signaling during amyloid pathogenesis might instead activate pro-inflammatory processes." (PMID 29490706, 2018). "Up-regulation of Csf1r is reported both in amyloid model of mouse and post-mortem human samples." (PMID 28934252, 2017). "Moreover, other study reported that 5.5-month administration of PLX5562, a CSF1R inhibitor, to 5xFAD mice at 1.5 months of age prevented the amyloid plaque formation but had no beneficial effect on hippocampal dependent memory." (PMID 32756440, 2020). "However, although neuroinflammation was highly dampened in these microglia-ablated mice, amyloid plaque pathology was not altered by CSF1R inhibition." (PMID 30241479, 2018). "However, elimination of microglia using inhibitors to CSF1R that plays an essential role in microglial survival, proliferation, and function, exerts protection in AD model mice with or without affecting amyloid plaque burden." (PMID 39695808, 2024). "Our data support the hypothesis that CSF1R engagement by Csf1 critically modulates microglial subsets and transcriptional states in amyloid pathology by reshaping the functionality of the non-PAM–PAM axis, reducing clonal expansion around the amyloid plaque and enhancing phagocytic activity." (PMID 40659845, 2025).
Arthritis (17 papers, 2010 to 2025). Inflammation of a joint. "The authors largely focus on bone conditions, highlighting mouse studies in which CSF1R-blocking drugs were shown to ameliorate bone loss and inflammatory symptoms in models of arthritis, osteoporosis and metastatic cancer." (PMID 32801364, 2020). "With regard to experimental arthritis, it is interesting to note that the lack/blockade of CSF-1 as well as the blockade of CSF-1R is associated with less severe methylated bovine serum albumin (mBSA)-induced arthritis and CIA." (PMID 30886947, 2017). "JNJ-40346527 (Edicotinib), a selective inhibitor of colony-stimulating factor-1 receptor (CSF-1R) tyrosine kinase that was originally evaluated for arthritis, inflammatory bowel disease, and cancer is being tested in a phase 1 trial in patients with MCI." (PMID 37277738, 2023). "Pharmacological inhibitors of CSF1R reduced the inflammatory activation of RA synovial tissue and severity of experimental arthritis." (PMID 38132128, 2023). "A similar pro-inflammatory function of CSF1R signaling has been described in an animal model of arthritis, where antibody blockade of CSF1R signaling significantly reduced the inflammatory response and ameliorated disease-related symptoms." (PMID 29490706, 2018). "CSF-1 or IL-34 stimulation of CSF1R promotes macrophage differentiation, activation and osteoclastogenesis, and pharmacological inhibition of CSF1R is beneficial in animal models of arthritis." (PMID 27036883, 2016). "Animal models have shown that exogenous administration of CSF-1, like GM-CSF, exacerbates the incidence and severity of CIA, while anti-CSF-1 Ab, genetic deletion of CSF-1, and pharmacological inhibitors of CSF1R reduce the severity of experimental arthritis." (PMID 27036883, 2016). "Given the efficacy of CSF1R blockade in RA synovial tissue, we examined the effect of the blocking anti-mouse CSF1R antibody muAB5 in vivo using the murine CIA model of arthritis." (PMID 27036883, 2016). "Given that the expression of IL34 and CSF1 are both elevated in arthritis, and that CSF1R signaling is critical for macrophage differentiation and osteoclast homeostasis, we asked whether CSF1 and/or IL34 neutralization affected arthritis disease induction and outcome." (PMID 31552020, 2019).
osteosarcoma (17 papers, 2014 to 2025). A usually aggressive malignant bone-forming mesenchymal neoplasm, predominantly affecting adolescents and young adults. "In human osteosarcoma cell lines, a pool of CSF-1R+ cells was identified and receptor expression was associated with mesenchymal marker expression and invasive capabilities, as CSF-1R genetic ablation inhibited EMT and the migration of tumor cells." (PMID 38254773, 2024). "Interestingly, CSF-1R expression has been found to be associated with good prognosis in osteosarcomas, which is in line with the reported protective function of TAMs in osteosarcomas." (PMID 34440251, 2021). "This interaction has been previously identified in osteosarcoma, and targeting this axis in cell lines and patient-derived xenografts using the CSF1R inhibitor pexidartinib inhibited tumor and metastatic growth." (PMID 40647416, 2025). "The prevalence of TAMs and their correlation with poor prognosis in osteosarcoma suggests that inhibitors of CSF1R are a reasonable agent in osteosarcoma treatment." (PMID 37361567, 2023). "In leiomyosarcomas and osteosarcomas, CSF-1R was found to be highly expressed by TAMs, and, in leiomyosarcomas, expression of CSF-1 and related proteins have also been associated with worse clinical outcomes." (PMID 34440251, 2021). "This strategy also yielded results in canine osteosarcoma—the CSF-1R inhibitor toceranib showed efficacy in 11 out of 23 patients treated." (PMID 32961800, 2020). "Additionally, CSF1, expressed on osteosarcoma cells, interacts with CSF1R, which is highly expressed in the macrophages." (PMID 40647416, 2025). "Moreover, the role of CSF1R in osteosarcoma has also been studied, but CSF1R is mainly expressed in TAMs rather than OS tumor cells." (PMID 37361567, 2023). "The FDA-approved CSF1R inhibitor PLX3397 can suppress the growth of osteosarcoma in mice." (PMID 35814015, 2022). "Low-expressed CSF1R could impede the growth and metastasis of osteosarcoma cells though inactivating ERK signaling." (PMID 35340229, 2022). "In this study, CSF1R was identified as a potential target of miR-22-3p, which suggests that the increased CSF1R induced by miR-22-3p downregulation is one of the reasons for osteosarcoma development." (PMID 35340229, 2022). "Blocking CSF-1R in a mouse osteosarcoma model led to fewer lung metastases and prolonged survival." (PMID 32961800, 2020). "Finally, we chose to make some contributions to the research on CSF1R in osteosarcoma." (PMID 35814015, 2022). "In addition, we found some studies on CSF1R in osteosarcoma in the past five years." (PMID 35814015, 2022). "Addition of a CSF-1R inhibitor potentiates and overcomes resistance to checkpoint inhibitors in other solid tumour models, suggesting that combination of a checkpoint inhibitor with a CSF-1R inhibitor could have potential in osteosarcoma therapy." (PMID 32961800, 2020). "Osteosarcoma cells polarized macrophages to an M2 phenotype via CSF1 and CSF1R, and interactions between LYVE1+ and angiogenic macrophages through CCL2 and CCR1 promoted a proangiogenic niche and inflammatory responses." (PMID 40647416, 2025). "Here, we investigated the effect of sulfatinib, a multi-targeted tyrosine kinase inhibitor (TKI) of FGFR1, CSF1R, and VEGFR1–3, on the treatment of osteosarcoma (OS)." (PMID 37361567, 2023). "In summary, this study suggests the miRNAs including miR-22-3p, miR-154-5p, miR-34a-5p, miR-485-3p, miR-93-5p, and miR-9-5p and the genes including LEF1, RUNX2, CSF1R, CDKN1A, and FBN1 are the key factors in the progression of osteosarcoma." (PMID 35340229, 2022). "Through the comprehensive integration of GO, KEGG pathway analysis, and Cytoscape software analysis results, four osteosarcoma key genes, MMP9, FERMT3, CSF1R, and VWF, were finally identified." (PMID 35814015, 2022).
osteosarcoma (continued). "In conclusion, this study suggested that the miRNAs including miR-22-3p, miR-154-5p, miR-34a-5p, miR-485-3p, miR-93-5p, and miR-9-5p and the genes including LEF1, RUNX2, CSF1R, CDKN1A, and FBN1 act as key factors in the progression of osteosarcoma." (PMID 35340229, 2022). "In the study, by the method of bioinformatics analysis, the possible key genes of osteosarcoma including MMP9, FERMT3, CSF1R, and VWF were screened from two microarray datasets, GSE12865 and GSE36001." (PMID 35814015, 2022). "Thus, this study suggests that the hub nodes LEF1, RUNX2, CSF1R, VAV3, FZD3, CDKN1A, and FBN1 are key factors in the progression of osteosarcoma." (PMID 35340229, 2022). "On the other hand, relative to other pediatric solid tumor types, we observed osteosarcoma to exhibit pronounced expression of additional immunosuppressive molecules particularly TGFB1 and CSF1R, where median expression was the highest among all tumor types in the study cohort." (PMID 34818552, 2021).
lymphoma (16 papers, 2014 to 2025). A malignant (clonal) proliferation of B- lymphocytes or T- lymphocytes which involves the lymph nodes, bone marrow and/or extranodal sites. "The distribution of CSF1R protein in tonsil was also compared, using double immunoenzymatic labelling technique, with other markers of the microenvironment known to be associated with lymphoma pathogenesis, for example, FOXP3, PD-1 and the cytotoxic marker Granzyme B." (PMID 26066800, 2015). "Malignant T cells promote the expansion and proliferation of LAM, which are a bone fide dependency in these lymphomas, and are effectively depleted with a dual CSF1R/JAK inhibitor." (PMID 36970721, 2022). "Together, these reports highlighted the therapeutic potential of CSF1R blockade in treatments of leukemia or lymphoma, but further investigation is needed in the clinical setting to better define its role." (PMID 31783588, 2019). "We detected the signal of CSF1R in the lymphoma tissues of DLBCL patients by the immunohistochemistry (data not shown), and the signal was likely due to macrophages, but not DLBCL cells, in the tissues." (PMID 31417675, 2019). "The distribution of CSF1R+ cells varied greatly between the different lymphoma types and was restricted to macrophages and other monocytic cells in the microenvironment." (PMID 26066800, 2015). "A new monoclonal antibody, FER216, was generated to investigate CSF1R protein distribution in formalin fixed tissue samples from 24 reactive lymphoid tissues and 187 different lymphoma types." (PMID 26066800, 2015). "Here we describe for the first time, the protein expression and cell distribution of CSF1R using a thoroughly validated new monoclonal antibody (mAb) in a large series of normal lymphoid tissues and major lymphoma types, with particular emphasis on cHL." (PMID 26066800, 2015). "Moreover, MyD88-L265P-driven lymphomas enriched for PU.1 and C/EBPβ gene sets, and exhibited high-level expression of the respective TF and their target genes, such as Csf1r and Il1b." (PMID 40159497, 2025). "Alternatively, we hypothesized that it may depend on CSF1/CSF1R pathway activation, as in solid cancers and lymphoma, which was confirmed by the abrogation of CD163 expression induced by AML CM supplemented with GW2580 or PLX3397." (PMID 34771453, 2021). "We next sought to determine if anti-CSF-1R therapy could increase the efficacy of standard lymphoma immunotherapy (anti-CD20 rituximab)." (PMID 33731849, 2021). "Distribution of CSF1R immunohistochemical expression in lymphomas." (PMID 26066800, 2015). "The current study describes one such reagent recognising CSF1R, which could represent an important tool in the future study of cHL and other lymphomas." (PMID 26066800, 2015). "CSF-1R protein expression could represent an important tool in the future study of some lymphomas." (PMID 33562694, 2021). "In general, most low-grade lymphomas had fewer CSF1R+ TAMs macrophages in their microenvironment, whereas DLBCL, T-cell lymphomas and cHL had higher CSF1R+ cell counts." (PMID 26066800, 2015). "Pacritinib, a dual CSF1R/JAK inhibitor, effectively impaired LAM viability and expansion, prolonged survival in preclinical T-cell lymphoma models, and is currently being investigated as a novel therapeutic approach in these lymphomas." (PMID 36970721, 2022). "Of note, CSF-1R inhibition hampered FL-M2 positive crosstalk whereas it did not affect the viability of lymphoma cells in monoculture." (PMID 33731849, 2021). "The antitumoral effects of CSF1 blockade was also observed in mantle cell lymphoma where treatments with GW2580, a CSF1R inhibitor reduced lymphoma cell survival, irrespective of their sensitivity to ibrutinib, a Bruton’s tyrosine kinase (BTK) inhibitor." (PMID 31783588, 2019). "Despite increasing evidence of the role of TAMs in the lymphoma microenvironment, there is a lack of consistent information about the distribution of the CSF1R protein in normal and neoplastic tissues." (PMID 26066800, 2015).
lymphoma (continued). "A high-throughput screen demonstrated that PTCL-derived cytokines led to relative resistance to CSF1R selective inhibitors, and culminated in the identification of dual CSF1R/JAK inhibition as a novel therapeutic strategy to deplete LAM in these aggressive lymphomas." (PMID 36970721, 2022).